HOTAIRM1 (HOXA transcript antisense RNA, myeloid-specific 1)
Synonyms: HOXA-AS1; NCRNA00179; HOXA1-AS1
Gene: Long non-coding RNA gene on chromosome 7 (27,095,647 to 27,100,265, forward strand). Ensembl gene ENSG00000233429.
Diseases named in the same sentence as HOTAIRM1 in open-access papers:
HOTAIRM1 is named in the same sentence as 76 diseases in open-access papers, as found by Europe PMC text mining. Sharing a sentence is not in itself a finding about the gene and the disease. The quoted sentences say what the papers report.
glioma (28 papers, 2017 to 2024). A benign or malignant brain and spinal cord tumor that arises from glial cells (astrocytes, oligodendrocytes, ependymal cells). "By directly regulating the expression of HOXA1, HOTAIRM1 has been implicated in the promotion of tumor malignancy in lung cancer and glioma." (PMID 39553554, 2024). "The findings of our study demonstrate the oncogenic role of HOTAIRM1 in glioma progression and deepens the understanding of the underlying mechanism of HOTAIRM1 involved in glioma." (PMID 38012763, 2023). "Consistent with these prognostic associations, HOTAIRM1 was recently shown by other investigators to be aberrantly expressed in glioblastoma and associated with shorter survival of glioma patients." (PMID 34584066, 2021). "HOTAIRM1 knock-down cells showed increased ROS levels compared to control cells, a finding in line with the proteogenomic results suggesting deficient mitochondrial function in HOTAIRM1 knock-down glioma cells." (PMID 34584066, 2021). "Another lncRNA that is highly upregulated in gliomas and is associated with poor patient survival outcomes is HOTAIRM1." (PMID 33800703, 2021). "To further investigate the phenotypic changes caused by HOTAIRM1 knock-down, we generated stable knock-down glioma lines using a lentiviral shRNA approach." (PMID 34584066, 2021). "For example, overexpression of lncRNA HOTAIRM1 was associated with the immune activation in glioma tissues, whose character lied in enhancing T cell-mediated response and inflammatory response." (PMID 33330055, 2020). "To summarize, HOTAIRM1 level was positively associated with glioma tumor grade, and GBM had the highest expression level." (PMID 33323548, 2020). "In this study we found a close association between HOTAIRM1 expression and the clinical and molecular characteristics of glioma." (PMID 31477638, 2019). "Samples from the TCGA and CGGA datasets were arranged according to increasing HOTAIRM1 expression level and the association between HOTAIRM1 expression and clinical and molecular features of glioma was examined." (PMID 31477638, 2019). "To address this point, we analyzed TCGA and CGGA cohorts and found that HOTAIRM1 upregulation was independently associated with poor prognosis in glioma patients." (PMID 31477638, 2019). "To determine the relationship between HOTAIRM1 expression and glioma malignancy, we analyzed the association between HOTAIRM1 level and WHO grade and molecular classification." (PMID 31477638, 2019). "Thus, aberrant HOTAIRM1 expression is associated with a distinct immune and inflammatory phenotype in glioma." (PMID 31477638, 2019). "Thus, HOTAIRM1 is a better predictor of glioma patient survival than age, tumor grade, IDH mutation status, chemotherapy, and radiotherapy." (PMID 31477638, 2019). "In glioma stem cells, HOTAIRM1, through a ceRNA mechanism, forms the HOTAIRM1/miR-133b-3p/TGF-β regulatory loop, upregulating TGF-β to facilitate the metamorphosis of stem cells into CAFs." (PMID 39717771, 2024). "METTL3-dependent m6A modification imparts HOTAIRM1 stability in glioma cells, and m6A-modified HOTAIRM1 transcript plays a vital role in the promotion of VM formation." (PMID 39691597, 2024). "The independent predictive value of HOTAIRM1 for glioma patient response to TMZ therapy and survival is noteworthy." (PMID 39553554, 2024). "Functional analysis further supports the role of HOTAIRM1 in promoting malignant behaviors, aligning with recent findings, establishing it as an onco-lncRNA in glioma." (PMID 39553554, 2024). "Glioma tumor stem cells, with high expression of HOTAIRM1, upregulate TGF-β expression, driving the transformation of stem cells into CAFs and promoting tumor growth." (PMID 39717771, 2024). "In glioma, IGFBP2 is closely associated with METTL3-mediated HOTAIRM1 via its m6A binding-domains and positively regulated by HOTAIRM1, thus promoting VM." (PMID 39691597, 2024).
glioma (continued). "analysis of TCGA and CGGA cohorts revealed that increased HOTAIRM1 expression is independently connected with a poor prognosis in glioma patients." (PMID 39553554, 2024). "In summary, our data demonstrate that HOTAIRM1 facilitates METTL3-mediated VM formation in glioma via up-regulating IGFBP2 expression (graphical abstract)." (PMID 38012763, 2023). "Previously, HOTAIRM1 has been shown to accelerate malignancy of glioma through regulating ZEB2, a competing endogenous RNA targeting molecule that interacts with miR-873-5p." (PMID 38012763, 2023). "As a result, HOTAIRM1 expression was successfully overexpressed or suppressed in transfected glioma cells." (PMID 38012763, 2023). "Nevertheless, the molecular mechanism of HOTAIRM1 in regulating glioma VM formation remains elusive." (PMID 38012763, 2023). "To clarify the role of HOTAIRM1 in glioma angiogenesis mimicry, we first detected HOTAIRM1 expression level in glioma cells and tissues using qRT-PCR." (PMID 38012763, 2023). "In the present study, we evaluated the role of HOTAIRM1 in VM formation and identified high HOTAIRM1 expression in glioma cells and tissue samples." (PMID 38012763, 2023). "We found that HOTAIRM1 presented up-regulation in glioma tissues and cells and overexpression of HOTAIRM1 facilitated glioma cell proliferation, migration, invasion, and VM formation." (PMID 38012763, 2023). "We also observed that HOTAIRM1 expression level was high in glioma tissue samples relative to controls, and further analysis revealed that HOTAIRM1 was more highly expressed in high-grade glioma tissue than in low-grade glioma tissue samples." (PMID 38012763, 2023). "Further analysis indicated that METTL3 depletion partially rescued the impact of HOTAIRM1 on glioma cell malignancy and VM formation." (PMID 38012763, 2023). "qRT-PCR and western blot assays were used to evaluate the gene and protein expression levels of HOTAIRM1 in glioma patient tissue samples and cell lines." (PMID 38012763, 2023). "Rescue assays demonstrated that METTL3 silencing counteracted the impact of HOTAIRM1 on glioma cell malignancy and VM formation capacity." (PMID 38012763, 2023). "HOTAIRM1 promotes malignant progression of transformed fibroblasts in glioma stem-like cells remodeled microenvironment via regulating miR-133b-3p/TGFβ axis." (PMID 38012763, 2023). "Relative to normal human astrocyte NHA cells, HOTAIRM1 level showed an evident increase in glioma cell lines U87 and U251." (PMID 38012763, 2023). "We also noticed that IGFBP2 was downregulated in glioma cells after HOTAIRM1 knockdown and IGFBP2 facilitated HOTAIRM1-triggered glioma cell malignancy and VM formation." (PMID 38012763, 2023). "METTL3 was found to post-transcriptionally stabilized HOTAIRM1 and positively regulated its expression in glioma cells." (PMID 38012763, 2023). "The role of HOTAIRM1 in glioma cell progression and VM formation was explored using a series of function gain-and-loss experiments." (PMID 38012763, 2023). "In this study, HOTAIRM1 presents up-regulation in glioma cells and tissue samples and overexpression of HOTAIRM1 promotes glioma cell malignancy and VM formation capacity both in vitro and in vivo." (PMID 38012763, 2023). "HOTAIRM1 overexpression promoted glioma cell proliferation, migration, invasion and VM formation in vitro and promoted glioma tumor growth and VM formation capacity in vivo." (PMID 38012763, 2023). "Mechanistically, HOTAIRM1 promotes VM formation mediated by METTL3 in glioma progression via regulating IGFBP2 expression." (PMID 38012763, 2023). "To clarify HOTAIRM1-IGFBP2 regulatory pattern in glioma cellular processes, we conducted rescue experiments." (PMID 38012763, 2023). "Mechanistically, METTL3 was highly expressed in glioma tissues and cells and was bound with HOTAIRM1 which stabilized HOTAIRM1 expression." (PMID 38012763, 2023).
glioma (continued). "Previously, HOTAIRM1 is also revealed to accelerate the malignant progression of glioma by regulating ZEB2, a competing endogenous RNA targeting molecule that interacts with miR-873-5p." (PMID 38012763, 2023). "Collectively, these results suggest that HOTAIRM1 silencing partially counteracts METTL3 mediated glioma cell malignancy and VM formation capacity." (PMID 38012763, 2023). "What’s more, they elucidated that intracellular ROS decrease mediated by HOTAIRM1 contributed to the radiation resistance in glioma." (PMID 35912271, 2022). "The authors suggested that HOTAIRM1 promotes malignancy of gliomas by acting as a sponge for miR-129-5p and miR-495-3p." (PMID 33800703, 2021). "RNA fluorescence in situ hybridization (FISH) demonstrated that HOTAIRM1 expression was positive correlated with glioma malignancy grades in tissues sections of clinical specimens." (PMID 33816233, 2021). "Previous studies have reported that HOTAIRM1 expression is increased in high-grade gliomas and in recurrent compared to primary glioblastomas." (PMID 34584066, 2021). "Clinical glioma samples (n = 10) were collected to further verify HOTAIRM1 expression, which was in accordance with the TCGA results." (PMID 33816233, 2021). "So far HOTAIRM1 has been reported to play various roles in many types of cancers, including non-small cell lung cancer, glioma, colorectal cancer, endometrial cancer, ovarian cancer, etc., but most of the mechanisms are not clear." (PMID 34262023, 2021). "TCGA survival curve analysis of gliomas showed that the survival of patients with high HOTAIRM1 expression decreased significantly." (PMID 33816233, 2021). "Associated with poor prognosis, Lnc HOXA transcript antisense RNA, myeloid-specific 1 (HOTAIRM1) was highly expressed in high-grade gliomas and t-FBs." (PMID 33816233, 2021). "HOTAIRM1 was the only lncRNA on chromosome 7 that was significantly upregulated in gliomas with chromosome 7 gain." (PMID 34584066, 2021). "In summary, the current studies showed that HOTAIRM1 was upregulated in t-FB and gliomas, it can promote malignant biological phenotype of t-FBs by regulating TGFβ via miR-133b-3p." (PMID 33816233, 2021). "Recently, HOTAIRM1 has been shown to promote glioma growth and invasion through up-regulation of HOXA1 expression, through long-range chromatin interactions within HOXA cluster genes and regulating SNAI2." (PMID 34584066, 2021). "HOTAIRM1 expression in gliomas was evaluated in The Cancer Genome Atlas (TCGA) database, indicating HOTAIRM1 upregulation in gliomas compared with adjacent normal brain tissue." (PMID 33816233, 2021). "Another report suggested that the knockdown of HOTAIRM1 suppresses the malignant behavior of gliomas and increases tumour cell sensitivity to TMZ." (PMID 33800703, 2021). "The elevated expression of HOTAIRM1 is positively associated with cell proliferative ability, EMT induction, and chemoresistance in glioma cells and with poor overall survival rates in glioma patients." (PMID 34202078, 2021). "To validate the radiosensitizing effect of HOTAIRM1 knock-down in vivo, we investigated an orthotopic xenograft glioma model using LN-229 control and HOTAIRM1 knock-down cells." (PMID 34584066, 2021). "The role of HOTAIRM1 in transformation and malignant phenotype of fibroblasts in glioma microenvironment was explored in the current studies, which also disclosed that miR-133b-3p was the target of HOTAIRM1 and can inhibit biological behaviors of t-FBs." (PMID 33816233, 2021). "The results showed that HOTAIRM1 was significantly increased in glioma tissues compared with normal brain tissues." (PMID 33323548, 2020). "The results indicate that HOTAIRM1 plays an important role in the malignancy of glioma and is a potential therapeutic target for its treatment." (PMID 31477638, 2019). "In vitro experiments revealed that HOTAIRM1 knockdown suppressed the malignant behavior of glioma and increased tumor sensitivity to temozolomide." (PMID 31477638, 2019).
glioma (continued). "HOTAIRM1 also enhanced the immunosuppressive microenvironment of glioma by recruiting Tregs and dendritic cells." (PMID 31477638, 2019). "To determine the association between HOTAIRM1 expression and overall survival (OS) of glioma patients, we dichotomized median HOTAIRM1 levels into high expression (high-exp) and low expression (low-exp) groups." (PMID 31477638, 2019). "GO analyses revealed that immune response and inflammatory activity in glioma were influenced by HOTAIRM1 level." (PMID 31477638, 2019). "HOTAIRM1 overexpression was associated with limited clinical benefit from TMZ treatment, whereas HOTAIRM1 knockdown decreased the IC50 for TMZ in two glioma cell lines." (PMID 31477638, 2019). "In the present study, HOTAIRM1 knockdown inhibited EMT in glioma by reducing the levels of mesenchymal cell markers and increasing those of epithelial cell markers." (PMID 31477638, 2019). "The results of an in silico analysis indicated that HOTAIRM1 promotes the malignancy of glioma by acting as a sponge for microRNA (miR)-129-5p and miR-495-3p." (PMID 31477638, 2019). "To this end, in the present study we investigated the clinical relevance of HOTAIRM1 overexpression by analyzing 946 glioma specimens in The Cancer Genome Atlas (TCGA) and the Chinese Glioma Genome Atlas (CGGA) databases." (PMID 31477638, 2019). "The results of this study demonstrate that HOTAIRM1 can serve as an independent factor for predicting glioma patient survival and response to TMZ chemotherapy." (PMID 31477638, 2019). "HOTAIRM1 exhibited significantly increased levels in high-grade glioma compared to low-grade glioma and normal brains, indicating its potential roles in glioma biogenesis and development." (PMID 30376874, 2018). "The presence of several lncRNAs like CRNDE, HOTAIRM1 and H19 among the upregulated transcripts, were in concordance with earlier reports on their oncogenic role in glioma." (PMID 30038703, 2018). "First, we examined the expression levels of HOTAIRM1 in tumor tissues from 40 patients with glioma (WHO I and II, n = 20; WHO III and IV, n = 20) and 20 normal brain tissues." (PMID 30376874, 2018). "Our results showed that HOTAIRM1 was significantly up-regulated in glioma tissues compared with that in normal brain tissues." (PMID 30376874, 2018). "In this study, we validated high expressed HOTAIRM1 by quantitative RT-PCR in glioma tissues (grade I-IV) and GBM cell lines." (PMID 30376874, 2018). "Despite being upregulated in glioma as a fetal lncRNA, the prognostic significance of HOTAIRM1 in this cancer type remains unclear." (PMID 39553554, 2024). "METTL3-dependent m6A modification stabilizes HOTAIRM1 in glioma cells." (PMID 39691597, 2024). "Consequently, further experiments are required to elucidate the molecular pathways and biological role of HOTAIRM1 in glioma." (PMID 39553554, 2024). "Finally, miR-133b-3p, which possibly targets TGFB1 transcripts, bound directly to the Lnc HOXA transcript antisense RNA, myeloid-specific 1 (HOTAIRM1) in high-grade gliomas and in malignant transformed fibroblasts." (PMID 38571882, 2024). "Notably, HOTAIRM1 silencing reversed the impact of METTL3 overexpression on glioma cell malignancy and VM formation." (PMID 38012763, 2023). "Furthermore, overexpression of HOTAIRM1 promoted glioma tumor growth and VM formation capacity in tumor xenograft mouse model." (PMID 38012763, 2023). "Therefore, we attempted to clarify the role and molecular mechanism of HOTAIRM1 in glioma progression and VM formation capacity." (PMID 38012763, 2023). "Collectively, these results suggest that HOTAIRM1 promotes glioma cell malignant behaviors." (PMID 38012763, 2023). "Moreover, we also found that HOTAIRM1 silencing induced significant reduction in IGFBP2 expression in glioma cells." (PMID 38012763, 2023). "Given that HOTAIRM1 was highly expressed in glioma cells, we hypothesized that it might play a malignant role in glioma cellular processes." (PMID 38012763, 2023).